NFATC4 (nuclear factor of activated T cells 4)
Diseases named in the same sentence as NFATC4 in open-access papers (continued):
Sharing a sentence is not in itself a finding about the gene and the disease.
cervical cancer (4 papers, 2020 to 2023). A primary or metastatic malignant neoplasm involving the cervix. "Accumulating bioinformatical analyses about immune-related genes (IRGs) indicated that NFATc4 was recognized as the key immune gene to predict the poor prognosis in cervical cancer and acute myelocytic leukemia (AML)." (PMID 35698138, 2022).
colorectal cancer (4 papers, 2022 to 2024). A primary or metastatic malignant neoplasm that affects the colon or rectum. "By contrast, Nfatc4 knockdown reversed the resistance of colorectal cancer cells to oxaliplatin caused by Camta1 knockdown." (PMID 35332122, 2022). "In addition, we show that protein phosphatase 3 catalytic subunit alpha (PPP3CA) is essential for the expression and phosphorylation of NFATc4 caused by Camta1 knockdown, as well as the proliferation, invasion, and chemoresistance of colorectal cancer cells." (PMID 35332122, 2022). "In order to clarify the role of NFATc4 in the oxaliplatin resistance of colorectal cancer regulated by CAMTA1, we conducted clone formation experiments and apoptosis detection respectively." (PMID 35332122, 2022). "To investigate the levels of CAMTA1 and NFATc4, we performed qPCR, western blotting, and immunohistochemical staining experiments using normal and colorectal cancer tissues collected from patients during surgery." (PMID 35332122, 2022). "The levels of CAMTA1 mRNA were significantly lower in colorectal cancer tissues than that in paired adjacent normal tissues, whereas the NFATC4 mRNA level was significantly higher in colorectal cancer tissues." (PMID 35332122, 2022). "By contrast, the NFATC4 mRNA level in colorectal cancer tissues from different patients was significantly higher than that in paired adjacent normal tissues." (PMID 35332122, 2022). "In order to further clarify the mechanism of action of CAMTA1/NFATc4 in oxaliplatin resistance in colorectal cancer, we analyzed the interaction between PPP3CA, CAMTA1, and NFATc4." (PMID 35332122, 2022). "In conclusion, the negative regulation of NFATc4 by CAMTA1 is involved in the oxaliplatin resistance of colorectal cancer." (PMID 35332122, 2022). "Further studies are necessary to elucidate the roles of NFATc4 phosphorylation and dephosphorylation in colorectal cancer." (PMID 35332122, 2022). "Furthermore, Camta1 knockdown upregulated nuclear factor of activated T cells, cytoplasmic 4 (Nfatc4) mRNA, and protein levels in colorectal cancer cells and downregulated the phosphorylated NFATc4 level." (PMID 35332122, 2022). "To understand the role of NFATc4, a transcription factor, in colorectal cancer, as well as to determine whether its expression could be affected by the manipulation of CAMTA1 expression, we used CAMTA1-overexpressed and CAMTA1-silenced colorectal cancer cells." (PMID 35332122, 2022). "By contrast, compared with the control, the highest percentage of NFATc4 immuno-positive cells was found in colorectal cancer tissues from mice in which Camta1 expression was silenced, whereas the lowest percentage was found in colorectal cancer tissues from mice treated with oxaliplatin." (PMID 35332122, 2022). "In order to further explore the mechanism of CAMTA1 regulating oxaliplatin resistance in colorectal cancer, we predicted the downstream target genes of CAMTA1 and analyzed the expression of NFATc4." (PMID 35332122, 2022). "Further functional studies are required to understand the roles of CMATA1 and NFATc4, as well as PPP3CA, in colorectal cancer." (PMID 35332122, 2022). "We also confirmed such observations in NFATc4 knockdown cells, indicating that the negative regulation of NFATc4 by CAMTA1 is related to oxaliplatin resistance in colorectal cancer." (PMID 35332122, 2022). "In colorectal cancer cells, CAMTA1 negatively regulates the expression of NFATc4." (PMID 35332122, 2022). "To determine whether CAMTA1, NFATc4, and PPP3CA interact in colorectal cancer cells, we performed qPCR, western blotting, and co-immunoprecipitation experiments." (PMID 35332122, 2022). "Interestingly, NFATC4 knockdown can reverse the chemoresistance of CAMTA1-silenced colorectal cancer cells to oxaliplatin, and this cellular event is partly mediated by an interacting protein, PPP3CA, which together with CAMTA1, competitively binds to NFATc4." (PMID 35332122, 2022).
melanoma (4 papers, 2020 to 2024). A malignant, usually aggressive tumor composed of atypical, neoplastic melanocytes. "(E) NFATC4-targeted expression patterns in melanoma cohort data from The Cancer Genome Atlas (TCGA)." (PMID 35894206, 2022). "(F) Statistics of NFATC4-targeted KM survival curves using the melanoma cohort data in TCGA." (PMID 35894206, 2022). "The melanoma patient cohort in TCGA was divided into two clusters according to the NFATC4 target genes expression patterns, and the patient cluster with a high expression of NFATC4 target genes had a lower survival rate." (PMID 35894206, 2022). "Inhibition of NFATc4 may be effective in melanoma treatment." (PMID 39822413, 2024).
Obesity (4 papers, 2019 to 2022). Accumulation of substantial excess body fat. "With obesity, NFATC4 is known to initiate inflammatory processes, and it is associated with increased cell death in older patients." (PMID 35629083, 2022). "NFATc4 was activated and translocated into nucleus during methionine-choline diet-induced NASH, while knockdown of NFATc4 inhibited both methionine-choline diet-induced NASH and obesity-related NASH in mice." (PMID 35698138, 2022). "Likewise, DHA acted on genes like BMPER3, NFATC4 and ADAM15, belonging to categories deregulated under obesity adding further evidence for a potential role of this PUFA in attenuating obesity-related AT inflammation." (PMID 30838002, 2019).
cognitive deficits (3 papers, 2015 to 2016). "NFATc2 was more active in AD patients with mild cognitive impairment, contrary to NFATc4 whose expression was mostly associated with severe dementia." (PMID 27597899, 2016). "Also postmortem studies showed that, in the hippocampus of patients, activation of NFATc4 correlates with cognitive deficits." (PMID 27034843, 2016). "In AD brains, various isoforms of NFAT demonstrate differential activation profiles with nuclear fractions of NFAT1 (also known as NFATc2) elevated in patients with mild cognitive impairment (MCI) while nuclear fractions of NFAT3 (NFATc4) are increased in AD patient brains." (PMID 25889879, 2015).
dementia (3 papers, 2016 to 2023). Loss of intellectual abilities interfering with an individual's social and occupational functions. "Increased NFATc2 activation was revealed in AD patients with mild cognitive impairments, whereas NFATc4 showed a high nuclear accumulation in patients with severe dementia and AD." (PMID 38077352, 2023). "In line with that, over-activation of CaN, enhancing nuclear localization of NFATc2 and NFATc4, correlated with increased dementia severity in the human hippocampus, while the subcellular localization of NFATc1 was cytoplasmic." (PMID 38077352, 2023). "Analysis of the human postmortem brain demonstrated that NFATc2 and NFATc4 accumulate in the hippocampus in subjects with mild cognitive impairment, severe dementia, and AD, respectively." (PMID 33800389, 2021). "The levels of amyloid β, which is known to increase in the brain according to the severity of dementia, was correlated with that of nuclear NFATc4." (PMID 33800389, 2021). "These authors observed increases in calcineurin A activity and more marked shifts of NFATc2 and NFATc4 to nuclear compartments in human hippocampus with increased dementia severity, while even in rapid-autopsy postmortem human brain tissue NFATc1 was unchanged." (PMID 27597899, 2016). "NFATc2 activation is especially critical in the early stages of AD, while selective NFATc4 activation occurs later when the control of neuronal Ca2+ homeostasis and reactive oxidative species production is lost, leading to further neurodegeneration, neuronal death, and ultimately, dementia." (PMID 38077352, 2023). "The accumulation of both CaN and NFATc4 (but not NFATc2) in the nucleus of hippocampal tissue positively correlated with a higher level of soluble Aβ, which steadily increased as the severity of dementia progressed." (PMID 38077352, 2023).
depression (3 papers, 2022 to 2025). "The data suggest that NFATc4 in the mPFC plays a role in depression-like phenotype and increases in blood levels of IL-6 of LPS-treated mice." (PMID 35064103, 2022). "Using two NFAT inhibitors and AAV for Nfatc4, we found that NFATc4 signaling in the mPFC might play a role in the sustained prophylactic effects of (R)-ketamine for LPS-induced depression." (PMID 35064103, 2022). "It is likely that (R)-ketamine or NFATc4 inhibitors may produce prophylactic effects for inflammation-related depression in humans." (PMID 35064103, 2022). "In conclusion, this study shows that NFATc4 signaling in the PFC might contribute to the prophylactic effects of (R)-ketamine in inflammation model of depression." (PMID 35064103, 2022). "It found that the nuclear factor of activated T-cells 4 (NFATc4) signalling pathway contributed to the prophylactic effects of R-ketamine in the PFC, reducing depression-like behaviour and systemic inflammation when applying the forced swim test (FST)." (PMID 40097854, 2025).
heart failure (3 papers, 2013 to 2021). Inability of the heart to pump blood at an adequate rate to meet tissue metabolic requirements. "Second, a number of mouse models that exhibit mid-embryonic demise from heart failure exhibit abnormal cardiac mitochondria and mitochondrial dysfunction, including mice lacking Dbh, Nfactc3/Nfatc4, Rxra, and Slc8a1." (PMID 25427064, 2014).
myeloma (3 papers, 2016 to 2022). "A20 myeloma cells were transfected with a vector expressing NFATc4-GFP fusion protein and nuclear NFAT translocation was induced by the exposure to thapsigargin in the presence or not of NPs." (PMID 36124235, 2022). "Polymorphisms in genes involved in nervous system function, NFATC1, NFATC4, and EDN1 were associated with CIPN in 646 myeloma patients treated with bortezomib, as were TCF4, DYNC1I1, and GJE1 in 139 myeloma patients treated with bortezmib." (PMID 35360655, 2022).
non-small cell lung carcinoma (3 papers, 2010 to 2022). A group of at least three distinct histological types of lung cancer, including non-small cell squamous cell carcinoma, adenocarcinoma, and large cell carcinoma. "Further underlining the role of NFATc4 in tumorigenesis, non-small lung cell cancer samples which were positively stained for oncogenic Cox2 displayed high expression levels of NFATc4 and the AP1 proteins c-Fos and c-Jun." (PMID 26697077, 2016). "Chen’s research revealed that the NFATc4 positive rate is 28.3% in tumor tissues and 1.3% in adjacent normal tissues from 159 non-small cell lung cancer patients." (PMID 35698138, 2022). "They found a positive correlation between the expressions of NFATc4 and COX-2 which were both overexpressed in non-small cell lung carcinoma." (PMID 35698138, 2022).
Anxiety (2 papers, 2022 to 2023). Intense feelings of nervousness, tension, or panic often arise in response to interpersonal stresses. "Moreover, some significant genes within these nominally significant overlapping pathways have been previously associated with pain problems and/or anxiety symptoms (e.g., the ZNRD1 gene; the MDK gene; the FOXO3 gene; the COMT gene; the NFATC4 gene)." (PMID 37146008, 2023).
atrial fibrillation (2 papers, 2013 to 2014). A disorder characterized by an electrocardiographic finding of a supraventricular arrhythmia characterized by the replacement of consistent P waves by rapid oscillations or fibrillatory waves that vary in size, shape and timing and are accompanied by an irregular ventricular response. "The isoforms NFATc3 and NFATc4 are active during pathophysiological conditions that affect the cardiovascular system, including atrial fibrillation and hypertrophy." (PMID 23533546, 2013).
esophageal cancer (2 papers, 2015 to 2016). A primary or metastatic malignant neoplasm involving the esophagus. "These gene pairs were distinct across cancer types in general, but some simultaneously occurred in different cancers, e.g., NFATC4/FAT1 appeared in both endometrial and lung cancers and PEG3/ZIM2 appeared in skin and esophageal cancers." (PMID 26212640, 2015).
hearing loss (2 papers, 2019 to 2024). "In Nfatc4-deficient mice, the ABR threshold shifts were significantly lower at all frequencies compared with the control mice after noise exposure, suggesting that Nfatc4 deficiency protects against noise-induced hearing loss in vivo." (PMID 31379853, 2019).
leukemia (2 papers, 2016 to 2020). A malignant (clonal) hematologic disorder, involving hematopoietic stem cells and characterized by the presence of primitive or atypical myeloid or lymphoid cells in the bone marrow and the blood. "As a nuclear factor, NFATC4 needs to activate downstream pathways to mediate the crosstalk between leukemia cells and Tregs." (PMID 33329712, 2020).
liver fibrosis (2 papers, 2022 to 2025). "Remarkably, it was found that the inhibition of calcineurin/NFATc4 signaling mediated by RCAN1.4 could retard liver fibrosis." (PMID 35698138, 2022). "In the aspect of oncogenesis, NFATc4 activation promoted the EGFR-stimulated process of acinar-to-ductal metaplasia in pancreas and NFATc4 was activated in the NASH and liver fibrosis." (PMID 35698138, 2022).
lung carcinoma (2 papers, 2015 to 2022). "Although the research of NFATc4 in lung carcinoma is a bit less, NFATc4 has presented relatively high expression in lung cancer and involved in radiotherapy and the prognosis." (PMID 35698138, 2022). "Another research reported that knockdown of NFATc4 expression resulted in a radioprotective effect on A549 lung cancer cell line." (PMID 35698138, 2022).
optic neuropathies (2 papers, 2024). "Using the optic nerve crush (ONC) model, widely employed to study optic neuropathies and central nervous system axon injury, we found that NFATc4 is specifically but transiently up-regulated in response to mechanical injury." (PMID 38639863, 2024). "The synergistic effect of NFATc4 downregulation along with other known axon regeneration promoters may provide an effective combinatorial strategy to improve vision impairments in optic neuropathies." (PMID 38639863, 2024). "In summary, this study is the first to demonstrate that NFATc4 knockout may confer transient RGC neuroprotection and decelerate axonal degeneration after injury, providing a potent therapeutic strategy for optic neuropathies." (PMID 38639863, 2024). "NFATc4 knockout in mice enhances RGC survival and delays axonal degeneration following optic nerve injury by suppressing pro-apoptotic signaling, highlighting NFATc4 as a potential therapeutic target for optic neuropathies." (PMID 39458902, 2024).
skin cancer (2 papers, 2021 to 2022). "NFATc4, a stress response transcriptional factor, was found overexpressing in many skin cancer cell lines comparing with HaCaT cells." (PMID 35698138, 2022). "Of note, both CDK3 and NFATc4 are highly expressed among various types of skin tumor tissues compared with normal tissues." (PMID 35698138, 2022). "Further study elucidated that CDK3 phosphorylated NFATc4 at Ser259 and enhanced NFATc4 effect on skin cancer, and EGF treatment could promote CDK3/NFATc4-mediated cell transformation and proliferation." (PMID 35698138, 2022). "Overexpressing NFATc4 increased the cell proliferation, colony formation, migration, invasion, as well as tumor volume, while knockdown of NFATc4 by siRNA or inhibiting NFATc4 activity by tacrolimus (FK506) or ascomycin (FK520) suppressed skin cancer cell migration and invasion." (PMID 35698138, 2022). "The ectopic expression and activation of NFATc4 may markedly facilitate the progress of skin cancer." (PMID 35698138, 2022).
Type 2 Diabetes (2 papers, 2018 to 2024). "In conclusion, elevated IL-18, NFATC4, TNF-α, and IL-6 levels suggest inflammation is key in prediabetes pathogenesis, highlighting the need for further research into interventions to delay or prevent type 2 diabetes." (PMID 40027364, 2024).
adrenal hyperplasia (1 paper, 2023). "In agreement with our results, NFATC4 was found to be upregulated in a mouse model of adrenal hyperplasia expressing constitutively active β-catenin specifically in the ZG." (PMID 37310791, 2023).
chronic pancreatitis (1 paper, 2016). A chronic inflammatory process causing damage and fibrosis of the pancreatic parenchyma. "Lastly, we observed increased NFATc4 staining in the nuclei of cells within the metaplastic areas of a tissue from a patient with chronic pancreatitis." (PMID 26697077, 2016). "Consistent with our analyses in human chronic pancreatitis samples, NFATc4 expression in ADM areas in response to caerulein administration was predominantly detected in the nucleus, thus indicating activity of the transcription factor." (PMID 26697077, 2016).
Crohn disease (1 paper, 2023). A gastrointestinal disorder characterized by chronic inflammation involving all layers of the intestinal wall, noncaseating granulomas affecting the intestinal wall and regional lymph nodes, and transmural fibrosis. "NCOR2, NFATC4 and PAXBP1 code for transcription-associated factors and their dysregulations are linked to Crohn's disease, carcinogenesis and myopathic hypotonia, respectively." (PMID 37026480, 2023).
Down syndrome (1 paper, 2009). "Two NFATC negative regulators both locate to the Down syndrome critical region of human Chromosome 21, Nfatc2−/− and Nfatc4−/− double-knockout mice have physical and cognitive features resembling human Down syndrome." (PMID 19468298, 2009).
genital wart (1 paper, 2025). "The increased expression of GZMB, IFNG, IL-12B, and IL-8 and the decreased expression of NFATC4 and IL-7 in genital wart samples were highlighted." (PMID 40142865, 2025).
glioblastoma (1 paper, 2022). The most malignant astrocytic tumor (WHO grade IV). "NFATc4 was required and activated in doxorubicin-mediated cell death as well as doxorubicin-induced inhibition of cell migration and invasion in glioblastoma cell lines." (PMID 35698138, 2022).
Hyperkalemia (1 paper, 2023). An abnormally increased potassium concentration in the blood. "Inhibition of Cn/NFATC4 signaling may explain low plasma aldosterone levels and hyperkalemia in patients treated with tacrolimus, and the Cn/NFATC4 pathway may provide novel molecular targets to treat primary aldosteronism." (PMID 37310791, 2023).
injury (1 paper, 2020). Damage inflicted on the body as the direct or indirect result of an external force, with or without disruption of structural continuity. "Furthermore, NFATc4 subtype upregulated the pronociceptive cytokines in DRG and contributed to the chronic pain after nerve injury." (PMID 33070779, 2020).
myeloid leukemia (1 paper, 2016). A clonal proliferation of myeloid cells and their precursors in the bone marrow, peripheral blood, and spleen. "In another study, NFATc4 levels were significantly increased in brains of APP/PS1 transgenic mice (AD model) and NFATc4 overexpression increased Aβ production in human myeloid leukemia SAS-1 cells, suggesting a role for NFATc4 in amyloidogenesis." (PMID 27597899, 2016).
parasite infection (1 paper, 2013). "Moreover, NFATc4 was present in the cytoplasm of untreated cardiac cells, but upon parasite infection of ET-1-stimulated cardiomyocytes, it was translocated into the nucleus." (PMID 23409199, 2013).
pericardial effusion (1 paper, 2011). Fluid collection within the pericardial sac, usually due to inflammation. "It has been previously shown that dual deletion of NFATc3 and NFATc4 causes thin ventricles, decreased proliferation of ventricular myocytes and pericardial effusion culminating in embryonic lethality." (PMID 21779394, 2011).